STAT3 (signal transducer and activator of transcription 3)
Diseases named in the same sentence as STAT3 in open-access papers (continued):
Sharing a sentence is not in itself a finding about the gene and the disease.
breast cancer (continued). "Evidence that STAT3 plays a role in cellular differentiation and apoptosis, functions as a tumor suppressor, and regulates the in-cell process that decreases cancer cell invasiveness may be consistent with better outcomes in breast cancer patients with high pSTAT3." (PMID 35327992, 2022). "H53 also inhibited the PRL-induced phosphorylation of both STAT3 and STAT5, and AKT at a dose of 5-10 g/ml in T47D and MCF7 breast cancer cell lines, and further attenuated PRL-induced proliferation." (PMID 36714582, 2022). "The JAK/STAT family member STAT3 maintains GSCs and itself undergoes intronic A-to-I RNA editing to regulate its expression by alternative splicing in the MCF7 breast cancer cell line." (PMID 35133980, 2022). "By covalently linking a STAT3 siRNA and a CTLA4-specific aptamer, this conjugate successfully inhibits STAT3 activity, promotes tumor-infiltrating CD8+ T cell functions, and retards tumor growth of PyMT breast cancer under HFD feeding." (PMID 39872079, 2022). "In breast cancer, low expression of ZIC2 has been correlated with poor outcomes and acts as a tumor suppressor by regulating STAT3." (PMID 35565241, 2022). "The mammary-adipocyte-derived leptin activated STAT3 signaling to promote stemness and chemoresistance through transcriptionally induction of CPT-1b and activating FAO in breast cancer cells." (PMID 35646898, 2022). "In conclusion, our results clarified that during the communication between CAAs and breast cancer cells, CAA-derived LIF promotes breast cancer cell migration and invasion by activating the Stat3 signal." (PMID 35280694, 2022). "TRPM7 channel expression can regulate epidermal growth factor (EGF)-induced signal transducer and activator of transcription 3 (STAT3) phosphorylation and expression of the EMT marker vimentin in human breast cancer cells." (PMID 35359592, 2022). "PTPN9 suppresses the growth and invasion of breast cancer cells by negatively regulating HER2 and epidermal growth factor receptor (EGFR) and suppressing STAT3 activation." (PMID 35957898, 2022). "Taken together, mammary tumor progression is enhanced by this macrophage subset, which is mechanistically accumulated in the tumor stroma through FABP4 mediated miR-29b/IL-6/STAT3 cascade." (PMID 36060264, 2022). "In human breast cancer cells, MRE11 regulates cell proliferation via signal transducer and activator of transcription 3 (STAT3)." (PMID 36147632, 2022). "sought to determine the effect of G129R-hPRL on STAT3 activation, and identified that hPRL activated STAT3 preferentially compared to STAT5 in T47D breast cancer cells." (PMID 36714582, 2022). "The exception is the AKT/ERK1/2/STAT3 pathway, which is affected by CD36 silencing or blocking in breast cancer, HCC, leukemia, GBM, cervical cancer, and CRC." (PMID 36568966, 2022). "Under hypoxia, p-STAT3 interacts with PD-L1 to promote its nuclear translocation and enhances gasdermin C (GSDMC) transcription, thereby inducing pyroptosis in breast cancer (BC) cells." (PMID 35907881, 2022). "EEF2K has been reported to reduce the expression of PKM2 in breast cancer, and interact with PKM2 to regulate the phosphorylation of STAT3 in lung cancer." (PMID 35184394, 2022). "In breast cancer, NIC can effectively inhibit the STAT3 activation markers pY705 and pS727 and reduce the STAT3 dimerization capacity, thus significantly reducing the cell proliferation capacity." (PMID 36555754, 2022). "For breast cancer cells, IL-6/JAK/Stat3 signaling pathway is essential to maintain the CSCs property (CD44+CD24− cells), which suggested a prospective therapy mean to target the stem-like breast cancer cells." (PMID 36678534, 2022). "At the same time, in HER2-positive breast cancer, NCAPG promotes the development of trastuzumab resistance by activating the SRC/STAT3 axis." (PMID 35254214, 2022).
breast cancer (continued). "Worth emphasizing is, JAK2 /STAT3 is a prerequisite for the maintenance and proliferation of CSC of breast cancer and developing of chemo- and radio-resistance." (PMID 33672756, 2021). "We next examined the effect of TA on the phosphorylation of STAT3 and S6K1 in the MCF10A human mammary epithelial cell line overexpressing MYC and the MDA-MB-468 breast cancer line." (PMID 35095503, 2021). "MRTF-A can cooperate with signal transducer and activator of transcription 3 (STAT3) in inducing BRSM1 hypermethylation and increasing breast cancer invasion." (PMID 33652780, 2021). "STAT3 suggested as a METTL8 transcription factor in the previous study, is shown to have a lower correlation than YY1 in breast cancer." (PMID 34063990, 2021). "NOTCH4/STAT3 crosstalk is also important for epithelial-mesenchymal transition of breast cancer cells and NOTCH inhibition reduced the level of activated STAT3." (PMID 33530306, 2021). "The Michael acceptor moiety of SKSI-0412 has been predicted to bind to the cysteine 259 site of STAT3 and repress Tyr-705 phosphorylation and STAT3 translocation, leading to the induction of autophagy in MCF 10A ras in the breast cancer cell line." (PMID 34445513, 2021). "Western blot analysis confirmed that pIRES2-SOCS2 transfection upregulated the expression of SOCS3 and reduced the levels of p-STAT3 and p-JAK in breast cancer cells." (PMID 34120621, 2021). "It was reported that the activation of NF-κB and the IL-6/STAT3 pathway can promote EMT in a variety of cancers and that blocking NF-κB reduces metastasis in breast cancer." (PMID 33855091, 2021). "In breast cancer, JAK/STAT3 was found to promote FAO in cancer stem cells via directly binding to the promoter of carnitine palmitoyltransferase 1B (CPT1B) that results in transcriptional activation of a key enzyme needed for FAO." (PMID 34766135, 2021). "A previous study showed that the nuclear interaction of Stat3 and EGFR occurs when the iNOS/NO pathway is activated in breast cancer." (PMID 34884765, 2021). "Multiple pathways such as nuclear factor-κB (NF-κB), JAK/STAT3, PI3K/AKT have been activated under therapeutic pressure in breast cancer and non-small cell lung cancer." (PMID 34095111, 2021). "The gene-therapy strategies were designed to inhibit the STAT3 signaling and improve the TME in the breast cancer model have proved the potential of STAT3 as a valid target for immunotherapy." (PMID 33957948, 2021). "Leptin also promoted cancer growth and progression by STAT3-mediated upregulation of MMP-13, HER2 and hsp90 in pancreatic and breast cancer cells respectively." (PMID 34588926, 2021). "For example, common pathways, including Notch, human epidermal growth factor receptor 2 (Her-2), NF-κB, and signal transducer and activator of transcription 3 (STAT-3), are targets of various treatmentoptions used against breast cancer." (PMID 34572272, 2021). "We have shown that activated STAT3 and activated TrkA can be found in triple-negative and HER2-enriched breast cancers and that the combined JAK2–STAT3/TrkA activation signatures are significantly enriched in these two subtypes." (PMID 34066153, 2021). "Part of the signaling pathway, at least in breast cancer cells, involves the leukemia inhibitory factor receptor (LIFR) and signal transducer and activator of transcription 3 (STAT3) signaling." (PMID 33596971, 2021). "In breast cancer cells, thioridazine has been found to inhibit self-renewal via DRD2-dependent STAT3 inhibition as well as induce a G1 cell cycle arrest independent of DRD2." (PMID 33922599, 2021). "Here, the authors screened several hypoxia inducible genes and identified the oncogenic role of MAFF in breast cancer metastasis and that it activates IL11/STAT3 pathway." (PMID 34262028, 2021). "For instance, it was reported that binding of anti-GRP78 antibodies to GRP78 on the surface of breast cancer MCF-7 cells suppresses their proliferation and migration mediated by the STAT3 phosphorylation." (PMID 34943954, 2021).
breast cancer (continued). "In HER2-positive breast cancers, IL-6 expression can induce CSC-positive phenotype through activating NF-κB and STAT3 pathways, thus driving tumorigenesis and promoting chemotherapy resistance." (PMID 34095111, 2021). "The specific inhibition of STAT3 has emerged as a promising strategy to improve the TME, immune surveillance, tumor progression and metastasis of breast cancer." (PMID 33957948, 2021). "Interleukin-6 (IL-6) and IFN-γ activate STAT3 and STAT1 proteins, which bind to the MUC1 promoter region to enhance gene transcription in breast cancer cells." (PMID 34681277, 2021). "In mammary tumor cells, radiation stimulated EMT through the IL-6/JAK/STAT3 signaling axis, which upregulated JAG1, DLL4, and Notch2 transcripts, and GSI addition effectively attenuated migration and mesenchymal markers expression in the irradiated cells." (PMID 34680255, 2021). "In TME of breast cancer, ERK/STAT3 cascade has emerged as a pivotal regulator to stimulate macrophage M2-like polarization and promote tumor progression and metastasis." (PMID 33957948, 2021). "Altogether, these results indicate that STAT3 and ERK1/2 inhibition decrease CD36 expression in co-cultured breast cancer cells." (PMID 34561446, 2021). "Further studies addressing the relationship between STAT3 and STAT5 SUMOylation and the development of breast cancer are still needed." (PMID 33968766, 2021). "IL6, one of the proinflammatory cytokines, promoted breast cancer growth and metastasis through IL6/JAK/STAT3 loop." (PMID 33593435, 2021). "A study found that the continuous activation of STAT3 and the overexpression of VEGFA occur with high frequency in breast cancer patients and contribute to chemoresistance and secondary malignancy." (PMID 34059068, 2021). "In breast cancer, miR-19a was found to be critical in the polarization of TAMs to M1-like phenotype, through targeting multiple oncogenes such as VEGF and STAT3, preventing breast cancer metastasis." (PMID 34179081, 2021). "In breast cancer, Sox2+ cancer cells, via activation of nuclear factor of activated T-cells (NFAT), STAT3 and NF-κB, express chemokines CCL3 and ICAM-1 and thus recruit TAMs into the TME." (PMID 34235155, 2021). "In the follow‐up study, we will investigate the effects of STAT3 signal pathway and CXCR4 on the development and metastasis of breast cancer at the animal level." (PMID 33955151, 2021). "For instance, Yamei Pang found that the NEAT1/miR-124/STAT3 axis regulated the progression of breast cancer, and NEAT1 and STAT3 displayed similar functions as in our study." (PMID 33546665, 2021). "Chemo-protective lipid mediators such as leptin, secreted by surrounding adipocytes, enhanced the STAT3 activated-FAO pathway, contributing to paclitaxel resistance and CSC self-renewal in breast cancer." (PMID 33804114, 2021). "Molecular links between central obesity and breast cancer have also been inferred to trigger oncogenic signaling pathways, including NFκB, JAK, STAT3, and AKT." (PMID 33801973, 2021). "The observation highlighted the therapeutic potentials of targeting STAT3 in TME, especially in breast cancer patients with high PD-L1 expression." (PMID 33957948, 2021). "The JAK2/STAT3 signaling pathway can up-regulate the expression of PD-L1 in CD169+ macrophages, but cannot up-regulate the expression of PD-L1 in breast cancer cells, thus avoiding immune surveillance." (PMID 34283088, 2021). "STAT3 bound to the 5′ region of the FGFBP1 gene in a human lung cancer cell line (NCI-H358) and breast cancer cells (HCC70 and T47D)." (PMID 34341336, 2021). "For example, a functional interaction between activated forms of STAT3 and STAT5 has been described in breast cancer." (PMID 34771512, 2021). "This is partially mediated by tyrosine 239/240 and tyrosine 313 residues of Shc1, which activate STAT3-dependent immunosuppression and inhibit STAT1-induced immune surveillance in breast cancer cells, respectively." (PMID 33807608, 2021).
breast cancer (continued). "The following is the role of STAT3-related immune cells (MDSCs, macrophages, DCs, and T cells) in the TME of breast cancer." (PMID 33957948, 2021). "In conclusion, this study has revealed that TINCR promotes tumorigenesis through a STAT3–TINCR–EGFR-feedback loop by recruiting DNMT1 and acting as a ceRNA in human breast cancer." (PMID 33446634, 2021). "Therefore, targeting STAT3 might be beneficial for medicating breast cancer." (PMID 34833950, 2021). "Its inhibition of BRK in turn prevented downstream phosphorylation of STAT3, and reduced proliferation of MDA-MB-231 and T-47D breast cancer cell lines." (PMID 33391524, 2021). "In breast cancers, LEG1 activates the downstream focal adhesion kinase/c‐Src pathway, which further stimulates ERK and STAT3 signalling leading to enhanced expression of survivin, and inhibits apoptosis and conferred drug resistance." (PMID 33932101, 2021). "Studies by the Heiko Hermeking group and Junjeong Choi group further confirmed that IL-6/STAT3 signalling facilitates the epithelial-mesenchymal transition (EMT) and metastasis of colorectal cancer cells (CRC) and breast cancer cells, respectively." (PMID 33546665, 2021). "Following the response induced by chemotherapeutic agents in breast cancer cells, both DOX and PTX promoted the expression of EZH2 and STAT3 at 48 h after 4 h of drug treatment." (PMID 33823894, 2021). "In a proof-of-principle experiment, we conditionally deleted the JAK1 tyrosine kinase in KRAS-transformed mammary cancer cells using the dual recombinase approach and found that lack of JAK1 was sufficient to block the constitutive activation of STAT3." (PMID 34675248, 2021). "Similarly, the knockdown of circNOLC1 inhibited the SP ratio in MDA-MB-231 and MDA-MB-468 cells, while the STAT3 overexpression reversed the inhibition, implying that the overexpression of STAT3 rescues circNOLC1 depletion-attenuated proliferation and cancer stem cell activity of breast cancer." (PMID 34789263, 2021). "STAT3 expression has also been correlated with reduced survival and poor prognosis in patients with ESCC, breast cancer, and lung cancer." (PMID 33660414, 2021). "Signal transducer and activator of transcription 3 (STAT3) is an oncogene involved in the stem cell-like characteristics, proliferation, metastasis, and chemoresistance of breast cancer cells." (PMID 33506060, 2021). "For example, isolinderalactone (a drug) induces apoptosis in breast cancer cells (MDA‐MB‐231) and inhibits the STAT3 signaling pathway by regulating hsa‐miR‐30c‐5p." (PMID 34586751, 2021). "STAT3 hyperactivation was also reported to correlate with SOCS2 silencing in ovarian and breast cancers." (PMID 34589421, 2021). "Knockdown of STAT3 expression by siRNA induced FAS‐mediated apoptosis in vitro and in vivo in breast cancer." (PMID 34155784, 2021). "For instance, interleukin-6 (IL6) produced by CAF can enhance the Signal transducer and activator of transcription 3 (STAT3) pathway activation, thus accelerating the proliferation of breast cancer cells." (PMID 33819917, 2021). "According to the literature, STAT3 signalling has been related to progression and poor response in breast cancer, and in particular to trastuzumab resistance in HER2-positive breast cancer." (PMID 34948097, 2021). "With the release of IL-6 and nitric oxide, phosphorylation of STAT3 and activation of the NOTCH signaling pathway, the crosstalk effects between MDSCs and breast cancer cells are activated." (PMID 34202411, 2021). "Leptin also has the ability to interfere with tamoxifen action in estrogen receptor positive breast cancer cell lines, due to its activation of ERK1/2 and STAT3 signal transduction pathways under estradiol stimulation." (PMID 33482868, 2021).
breast cancer (continued). "Herein we report, for the first time that STAT3 and TrkA are significantly co-overexpressed and co-activated in triple-negative breast cancer (TNBC) and HER2-enriched breast cancer, as shown by immunohistochemical staining and data mining." (PMID 34066153, 2021). "FAO inhibition has been shown to reduce tumor‐spheroid formation in breast cancer stem cells, while activation of FAO restores tumor‐sphere formation ability in STAT3‐inhibited cells." (PMID 34766135, 2021). "In melanoma and breast cancer cell lines, PERK mediated early induction of C/EBPδ through ATF4-independent pathways that involved at least in part Janus kinases and the STAT3 transcription factor." (PMID 34725321, 2021). "In this review, we intend to establish the interaction between STAT3 and immune cells in TME of breast cancer, focusing on the immune cells function and population." (PMID 33957948, 2021). "The proliferation of the cells was reduced by transfection of Stat3 S727A vector in both murine (C4HD) and human (T-47D) breast cancer cell as compared with the control cells transfected with wild type Stat3 or empty vector." (PMID 34440160, 2021). "Collectively, our study uncovered that TrkA is a novel activating kinase of STAT3, and their co-activation enhances gene transcription and promotes breast cancer stem cells in TNBC and HER2-enriched breast cancer." (PMID 34066153, 2021). "Intriguingly, in luminal breast cancers, IFN-β promotes stemness via induction of SOX2 and STAT3 activity." (PMID 35582030, 2021). "In breast cancer, lnc-BM increased JAK2 kinase activity to mediate oncostatin M- and IL-6-triggered STAT3 phosphorylation, promote ICAM1 and CCL2 expression, and mediate macrophage recruitment to the brain and consequently metastasis." (PMID 34123857, 2021). "On the contrary, the activation of FAO, driven by the JAK/STAT3 signaling pathway through regulation of CPT1B (a key enzyme facilitating FAO), was seen in paclitaxel-resistant breast cancer." (PMID 33804114, 2021). "This study, for the first time, demonstrated that Nar can interact with STAT3 and furthermore reduce its phosphorylation in MDA-MB-231 breast cancer cells." (PMID 33680016, 2020). "Overall, this thorough study strongly suggests IFN-I as a cancer stemness driver in breast cancer, SCC and GBM, involving activation of STAT1, STAT2, and STAT3." (PMID 32296435, 2020). "It was shown that the continuously activation of Stat3 related with the aberrant activation of JAK and c-SRC in breast cancer cells, and inhibition of Src damaged the activity of Stat3 DNA-binding." (PMID 32565740, 2020). "As an essential component, STAT3 participates in cell proliferation, apoptosis, metastasis, and EMT in breast cancer cells." (PMID 32503225, 2020). "By decreasing STAT3 signalling, apigenin reversed drug resistance by suppressing drug efflux in adriamycin-resistant MCF-7 breast cancer cell lines." (PMID 32731620, 2020). "In our study, we showed that tangeretin had antiproliferative effects on breast cancer cells and reduced BCSC proliferation or prevalence through a decrease in Sox2 expression by inhibiting Stat3 signaling." (PMID 32503228, 2020). "It inhibits the cell proliferation and metastasis by targeting Janus kinase 2 (JAK2)/signal transducer and activator of transcription 3 (STAT3)-mediated EMT process in GC and by targeting p21-activated protein kinase 2 (PAK2) in breast cancer." (PMID 33028884, 2020). "STAT3 activation by IL-23/IL23R and via IL-32β-induced VEGF leads to increased migration and invasion of breast cancer (BC) and gastric cancer (GC) cells." (PMID 31952344, 2020). "The mature adipocytes facilitate the invasive behavior of breast cancer cells and trigger an EMT-phenotype via paracrine IL-6/STAT3 signaling." (PMID 33123472, 2020).